LINC01342 (long independently transcribed non-coding RNA 1342)
Gene: Long non-coding RNA gene on chromosome 1 (1,137,017 to 1,144,056, forward strand). Ensembl gene ENSG00000223823.
Diseases named in the same sentence as LINC01342 in open-access papers:
LINC01342 is named in the same sentence as 1 disease in open-access papers, as found by Europe PMC text mining. Sharing a sentence is not in itself a finding about the gene and the disease. The quoted sentences say what the papers report.
cancer (1 paper, 2021). A tumor composed of atypical neoplastic, often pleomorphic cells that invade other tissues. "The identification of LINC01342 in human cancer cell biological functions demands further explorations." (PMID 34504061, 2021).